HMGB1 (high mobility group box 1)
Diseases named in the same sentence as HMGB1 in open-access papers (continued):
Sharing a sentence is not in itself a finding about the gene and the disease.
Myocardial fibrosis (16 papers, 2014 to 2025). "HMGB-1 signaling pathway has been reported to be associated with inflammatory response and myocardial fibrosis, therefore, resveratrol may improve diabetic cardiomyopathy by downregulating the HMGB-1 signaling pathway." (PMID 35739982, 2022). "This study demonstrated that DAPA treatment significantly reduced myocardial fibrosis, restored cardiac function, and inhibited the HMGB1/RAGE signaling activity in AF." (PMID 40989585, 2025). "In conclusion, radiation treatment significantly leads to weight loss, cardiac dysfunction and myocardial fibrosis, which can be ameliorated by consumption of DBT, involving regulation of Nrf2/HMGB1 pathway as probable underlying mechanisms." (PMID 36699071, 2022). "Other studies determined that HMGB1 blockade alleviates myocardial fibrosis, possibly interfering with the TLR2-HMGB1 ligand and cardiac autophagy." (PMID 32508664, 2020). "The degree of myocardial fibrosis 6 weeks after HMGB1 fragment treatment was assessed by picrosirius red staining and compared with control group." (PMID 30517097, 2018). "The HMGB1 group showed improved left ventricular ejection fraction, reduced myocardial fibrosis, and increased capillary density." (PMID 30517097, 2018). "Quantification of fibrotic area confirmed that the degree of myocardial fibrosis was significantly reduced in the HMGB1 group compared with the control group (16.6±3.8% vs 22.7±5.4%, respectively, p = 0.04)." (PMID 30517097, 2018). "A similar scenario has been described in the diabetic heart, the activated HMGB1 promote myocardial fibrosis and heart dysfunction." (PMID 27070323, 2016). "This study aims to investigate whether DAPA attenuates myocardial fibrosis in AF rats by modulating the HMGB1/RAGE signaling pathway." (PMID 40989585, 2025). "However, the potential role of DAPA in mitigating AF-related myocardial fibrosis via HMGB1/RAGE signaling remains insufficiently defined." (PMID 40989585, 2025). "We hypothesize that systemic administration of this HMGB1 fragment attenuates the progression of myocardial fibrosis and cardiac dysfunction in a hamster model of DCM by recruitment of BMMSCs, promoting self-regeneration." (PMID 30517097, 2018). "An increase in HMGB1 promoted the cardiomyocyte-dependent induction of myocardial fibrosis." (PMID 27821807, 2016). "Our previous study demonstrated that in diabetic condition, cardiomyocytes increase the expression of the high-mobility group box 1 (HMGB1) protein, which mediates cardiomyocyte–fibroblast communication, thus resulting in fibroblast collagen production and myocardial fibrosis." (PMID 27821807, 2016). "Given the cardio-protective effects of HMGB1 silencing, inhibition of HMGB1 may improve myocardial fibrosis and undoubtedly provide new target for its intervention." (PMID 25284457, 2014). "The present study shows that treatment with resveratrol can prevent HMGB1/RAGE/TLR4/NF-κB pathway, oxidative damage, myocardial fibrosis, and inflammation in STZ-induced type 1 diabetic hearts." (PMID 27833703, 2016). "To address this gap, we employed a rat model of AF to systematically evaluate DAPA’s effects on cardiac function, myocardial fibrosis, and inflammation, and found that DAPA exerts its cardioprotective actions in part by inhibiting the HMGB1/RAGE signaling pathway." (PMID 40989585, 2025). "Thus, the objective of the present study was to analyze the impact of intravenous administration of HMGB1 on the myocardial expression of VEGF, myocardial fibrosis, and cardiac function in rats subjected to acute myocardial I/R." (PMID 32063860, 2019).
neuropathy (15 papers, 2014 to 2024). A disorder affecting the nervous system that manifests with pain, tingling, numbness, and/or muscle weakness. "Cytoplasmic translocation and release of the redox-sensitive cytokine HMGB1 have been associated with oxidative stress during neuropathy of the CNS and ENS26,41." (PMID 38503815, 2024). "ADAMTS-13 and HMGB1 are valuable biomarkers for disease risk assessment, estimating host neuropathy following T. multiceps (c." (PMID 37863934, 2023). "It is likely that the amount of endogenous TLR4 ligands, like high mobility group box1 (HMGB1), is increased in painful neuropathy, binding to TLR4 and leading to the activation of the NF-κB pro-inflammatory cascade and the upregulation of TNFα." (PMID 37175520, 2023). "Curiously, the caspase 8 inhibitor significantly reduced bortezomib-induced macrophage release of HMGB1, preventing neuropathy." (PMID 35418856, 2022). "Minocycline and ethyl pyruvate (which inhibits HMGB1 release from macrophages) and macrophage depletion with liposomal clodronate prevented the appearance of neuropathy, but only minocycline abolished the established neuropathy." (PMID 35418856, 2022). "Further, many studies have found that anti-HMGB1 antibodies or drugs that promote degradation of HMGB1 reduce pain following nerve injury, LPS administration and other forms of neuropathy." (PMID 33392418, 2021). "Most interestingly, our data suggest that the oxaliplatin-induced neuropathy is largely independent of macrophages, which is in contrast to the critical role of macrophages as the origin of HMGB1 involved in paclitaxel-induced neuropathy in our previous study." (PMID 31666085, 2019). "Given the present evidence for the involvement of HMGB1 in oxaliplatin-induced neuropathy, HMGB1 is considered a common key molecule in the pathogenesis of CIPN caused by distinct chemotherapeutics." (PMID 31666085, 2019). "Hence, understanding the detailed involvement of TRPC6 and HMGB1 in painful neuropathy would presumably reveal possibilities for therapeutic interventions for this devastating condition." (PMID 32019145, 2020). "The increases in HMGB1 in the DRG and spinal cord dorsal horn neurons and release of HMGB1 may contribute to the maintenance of painful neuropathy in the diabetic animals." (PMID 32019145, 2020). "We thus examined whether HMGB1, particularly derived from macrophages, contributes to oxaliplatin-induced neuropathy in mice and analyzed the anti-neuropathic activity of the TM/thrombin system." (PMID 31666085, 2019). "Given our recent evidence for the critical role of macrophage-derived HMGB1 in paclitaxel-induced peripheral neuropathy, we asked whether oxaliplatin-induced neuropathy involved macrophages in mice." (PMID 31666085, 2019). "Besides, HMGB-1 was found to promote neuropathy via regulating MMP9, which reveals a possible role for HMGB-1/MMP9 pathway in neurodegeneration during DR." (PMID 27847406, 2016). "Thus, it could be predicted that TLR-induced HMGB1 translocation and release can drive further neuropathy." (PMID 36551259, 2022). "Here, we tested whether HMGB1 was involved in oxaliplatin-induced neuropathy in mice and rats." (PMID 31666085, 2019). "The pronociceptive role of HMGB1 in the dorsal root ganglia (DRG) and spinal cord has been further confirmed in the inflammatory pain mouse model of collagen antibody-induced arthritis and in rodents with surgical nerve injury induced neuropathy." (PMID 32019145, 2020). "Surprisingly, macrophages, which are responsible as an origin of extracellular HMGB1 for the paclitaxel-induced peripheral neuropathy, do not appear to contribute to the neuropathy in the oxaliplatin-treated mice." (PMID 31666085, 2019). "Thus, the authors proposed that HMGB1 derived from non-macrophage cells mediates oxaliplatin-induced neuropathy." (PMID 35418856, 2022).
neuropathy (continued). "In the present study, surprisingly, although we observed the full repertoire of changes from neuropathy within the peripheral nerves of diabetic mice, we did not discover definite changes in the sciatic nerve protein expression of RAGE or its ligand HMGB1 between experimental treatments." (PMID 34833143, 2021).
squamous cell carcinoma (15 papers, 2013 to 2025). A carcinoma arising from squamous epithelial cells. "Strong HMGB1 staining was linked to nodal metastases in high-grade serous ovarian carcinomas (p = 0.0213) and colorectal adenocarcinomas (p = 0.0137), as well as to poor histological grade in squamous cell carcinomas (p = 0.0010)." (PMID 40804938, 2025). "In this study, we examined the effects of brief (1 h) low‐frequency (20 Hz) mechanical vibration on glucose consumption and survival (apoptosis, necrosis, HMGB1 release) of the human epidermoid carcinoma cell line A431." (PMID 32647502, 2020). "In this tissue-based study, we examined the impact of the expression of autophagy-related proteins LC3B, p62, and HMGB1 in a consecutive cohort of squamous cell carcinomas of the lung." (PMID 30134604, 2018). "Immunohistochemistry results showed that HMGB1 was differentially expressed in epithelial intercellular spaces, with seborrheic keratosis and squamous cell carcinoma showing higher expression than normal skin." (PMID 23803172, 2013). "Also, upregulation of HMGB1 was found to contribute to radioresistance in squamous cell carcinoma by promoting chromatin modification and increasing the phosphorylation of CHK1 to activate DNA damage responses (DDR)." (PMID 33187536, 2020). "Expression of HMGB1 in inflammatory cells of seborrheic keratosis, precancerous lesions, basal cell carcinoma and squamous cell carcinoma was significantly higher than in normal skin (P = 0.0024); HMGB1 expression in inflammatory cells of benign seborrheic keratosis increased non-signigicantly." (PMID 23803172, 2013). "Moreover, since HMGB1 is overexpressed in both squamous cell carcinoma and esophageal adenocarcinoma, it could be used to extend the analysis to all esophageal tracts." (PMID 36978761, 2023). "Furthermore, the expression of HMGB1 in epithelial nuclei in squamous cell carcinoma was significantly lower than in normal skin and benign seborrheic keratosis (P <0.01), suggesting that HMGB1 maybe not account for epidermal tumor progression." (PMID 23803172, 2013). "The interaction between HMGB1 and RAGE enhances the migration activity of human squamous cell carcinoma SCC7 cells, while nifedipine dose-dependently inhibits the HMGB1-RAGE interaction in SCC cells." (PMID 38529373, 2024). "One study has shown that the infection of oncolytic HSV-1 within squamous cell carcinoma (SCC) cells, in vitro, increased the release of ATP and high mobility group box 1 (HMGB1) compared to uninfected SCC." (PMID 34207386, 2021). "We found that Hsp90, Annexin A1, and HMGB1 were largely released in the extracellular medium in response to either 1 or 10 μM OR141 in SCC7 and A431 squamous cell carcinoma cells." (PMID 31508370, 2019). "In squamous cell carcinomas, HMGB1 only differed between responders and non-responders before cycle 3, with responders possessing a higher median concentration (5.02 ng/mL vs. 2.10 ng/mL)." (PMID 33672622, 2021). "In highly malignant squamous cell carcinoma (SCC), there was relatively weak diffuse positive expression of HMGB1 in the cancerous epithelial nuclei, but minimal expression in the cytoplasm and scattered expression of HMGB1 in the epithelial intercellular spaces." (PMID 23803172, 2013).
temporal lobe epilepsy (15 papers, 2014 to 2025). A localization-related (focal) form of epilepsy characterized by recurrent seizures that arise from foci within the temporal lobe, most commonly from its mesial aspect. "Our findings indicate that ILF3‐AS1 contributes to hippocampal neuron injuries following temporal lobe epilepsy by inhibiting neuronal oxidative stress and inflammation through the miR‐504‐3p/HMGB1 pathway in vitro." (PMID 39135276, 2024). "Cytoplasmic HMGB1 staining was increased in human hippocampi specimens from drug-resistant temporal lobe epilepsy (TLE) with hippocampal sclerosis (TLE-HS) compared with control subjects." (PMID 31241711, 2019). "In a rat model of temporal lobe epilepsy, it has been shown that HMGB1/TLR4 is overexpressed and may induce inflammatory responses and reorganization of neuronal synaptic transmission through the p38MAPK signalling pathway." (PMID 39046369, 2024). "The anti‐seizure effect of the anti‐HMGB1 monoclonal antibody has been shown to have sufficient potential to treat seizures in both the kainic acid model and in tissue slices from patients with medically refractory temporal lobe epilepsy." (PMID 39046369, 2024). "The anti-seizure effect of the anti-HMGB1 monoclonal antibody showed sufficient potential and specificity for treating kainic acid-induced seizures in an animal model and surgical tissue slices from patients with medically refractory temporal lobe epilepsy." (PMID 35837232, 2022). "For example, TLR4 antagonists and BoxA, a competitive antagonist to HMGB1 comprising of the BoxA domain of the protein, have been reported to reduce and even inhibit epileptic activity that is resistant to standard ASDs in an animal model of temporal lobe epilepsy." (PMID 28086980, 2017). "Increased upregulation and expression of HMGB1 in animal models and human temporal lobe epilepsy (TLE) and modification of epileptic seizures upon treatment with antagonist of HMGB1 strengthen the role of HMGB1 in generation of epileptic seizure." (PMID 33732146, 2020). "Recently, two proinflammatory molecules were found to be proconvulsant in animal models of temporal lobe epilepsy (TLE): IL-1β and HMGB1." (PMID 24936172, 2014). "Parallel to our findings, HMGB1 release from neurons was reported to activate TLR4 in astrocytes but not microglia in mouse models of seizures, as well as specimens from patients with temporal lobe epilepsy with hippocampal sclerosis." (PMID 38082296, 2023). "Thus, through the hyperexcitability of the HMGB1/RAGE/TLR4/NF-kB signaling pathway, HMGB1 has a pro-epileptic impact that induces temporal lobe epilepsy development." (PMID 36310854, 2022). "Our results demonstrate a HMGB1 and IL-1β-mediated environmental anti-neurogenic effect in human TLE, identifying both the IL-1R and TLR 2/4 receptors as potential drug targets for restoring human hippocampal neurogenesis in temporal lobe epilepsy." (PMID 34548070, 2021). "The levels of cytoplasmic HMGB1 are upregulated in reactive glia and spinal cord neurons in amyloid lateral sclerosis (ALS) patients and similar expression of HMGB1 is observed in post-surgery hippocampal specimens from patients with drug-resistant temporal lobe epilepsy." (PMID 35216110, 2022).
vitiligo (15 papers, 2018 to 2025). Generalized well circumscribed patches of leukoderma that are generally distributed over symmetric body locations and is due to autoimmune destruction of melanocytes. "Our study showed that S100B was only correlated with affected BSA in active vitiligo, but HMGB1 was associated with the vitiligo severity in both the active and stable stages." (PMID 36569840, 2022). "Multivariate logistic regression analysis showed S100B (OR, 1.019; 95% CI, 1.002-1.038; P =0.03), S100A9 (OR, 1.002; 95% CI, 1.001-1.003; P<0.001), and HMGB1 (OR, 1.915; 95% CI, 1.186-3.091; P =0.008) were significantly associated with vitiligo activity." (PMID 36569840, 2022). "As both necroptosis and pyroptosis are lytic forms of cell death, they result in the uncontrolled release of inflammatory mediators such as high-mobility group box 1 (HMGB1), interleukin-33 (IL-33), and S100 alarmin proteins—all of which have been reported as markers associated with vitiligo." (PMID 41007740, 2025). "The findings demonstrated that although S100B was only correlated with the affected BSA in active vitiligo (r =0.60, P <0.001), HMGB1 was associated with the vitiligo severity in both the stable and active stages (stable phase, r=0.60, P <0.001; active phase, r=0.50, P <0.001)." (PMID 36569840, 2022). "Thus, we explored the association between S100B, S100A9, and HMGB1 and vitiligo severity in various disease activity phases." (PMID 36569840, 2022). "HMGB1 subsequently causes the production of chemokines in adjacent keratinocytes and the maturation of dendritic cells (DCs) in a paracrine way, which ultimately promotes the formation of cytotoxic T cells (CTLs) that undermine melanocytes in vitiligo." (PMID 34917229, 2021). "Clinical studies have demonstrated that HMGB1 was overexpressed in the serum and skin of vitiligo patients compared to healthy controls." (PMID 41169396, 2025). "Recent data have shown that HMGB1 is overexpressed in both blood and lesional samples from vitiligo patients." (PMID 40308590, 2025). "Our ROC analysis revealed that serum IL-1α, S100B, S100A9, and HMGB1 had predictive capacity on the diagnosis of vitiligo." (PMID 36569840, 2022). "In fact, HMGB1 is overexpressed in blood samples and lesional specimens from patients with vitiligo." (PMID 36154894, 2022). "Taken together, our findings support the protective effects of FA on human melanocytes against oxidative injury via the activation of Nrf2 and the inhibition of HMGB1, thus indicating FA as a potential therapeutic agent for the treatment of vitiligo." (PMID 34917229, 2021). "Given the proinflammatory role of HMGB1 secreted by melanocytes under oxidative stress in the immune pathogenesis of vitiligo the effect of FA on the status of HMGB1 in ROS-triggered melanocytes was examined at last." (PMID 34917229, 2021). "One of the most important mediators of inflammation in vitiligo is HMGB1 released from melanocytes primed by ROS." (PMID 34917229, 2021). "We think that this is the mechanism by which HMGB1 participates in the pathological process of vitiligo." (PMID 30338917, 2018). "This also explains the role of HMGB1 in the development of vitiligo and helps understand the mechanism of melanocyte death." (PMID 30338917, 2018). "We propose that external stressors, such as oxidative stress, regarded as precipitating factors in vitiligo, stimulate HMGB1 release from NHEMs, leading to melanocyte apoptosis." (PMID 30338917, 2018). "Consequently, HMGB1 is not only involved in the regulation of melanocyte survival and function but also exacerbates vitiligo progression by activating inflammatory and autoimmune responses." (PMID 41169396, 2025). "HMGB1 is also one of the DAMPs and their levels are increased in the sera of vitiligo patients." (PMID 37298700, 2023). "High mobility group box protein B1 (HMGB1) may be another important target for the treatment of vitiligo." (PMID 37298700, 2023).